PCNA (proliferating cell nuclear antigen)
Diseases named in the same sentence as PCNA in open-access papers (continued):
Sharing a sentence is not in itself a finding about the gene and the disease.
tumor (continued). "Specifically, irradiation reduced extracellular matrix deposition and enhanced tumor cell apoptosis (evidenced by increased cleaved caspase-3 and cytosolic PCNA) while PD-1 blockade stimulated robust inflammatory responses, in particular, expansion of CD8α+ T cell infiltration." (PMID 41208884, 2025). "The expression of PCNA in the tumor masses was also measured by real‐time PCR: rats treated with AuNR‐ECFCs showed a significant decrease in the gene expression of PCNA compared to control rats, thus confirming the anti‐proliferative effects already shown in the immunohistochemical analysis." (PMID 40545912, 2025). "In addition, immunohistochemical staining of these subcutaneous tumors demonstrated that the CFAP58-DT knockdown group exhibited a decrease in the expression of Ki67 and PCNA in tumor tissues." (PMID 40386064, 2025). "Additionally, KLH-PD-L1-SARS reduced the expression of PCNA in tumor cells, indicating a decrease in tumor cell proliferation." (PMID 41455906, 2025). "Moreover, the result of immunohistochemical (IHC) staining also revealed a marked decrease in PCNA protein levels in tumor tissue following BRD1 inhibition." (PMID 39962068, 2025). "Notably, PCNA is frequently overexpressed in highly proliferating tumor cells, where it functions as both a biomarker of uncontrolled proliferation and a promising therapeutic target." (PMID 40313621, 2025). "Furthermore, it upregulated the expression of the P21 gene while downregulating the expression of proliferating cell nuclear antigen (PCNA), thereby exerting cytotoxic effects on tumor cells." (PMID 40276599, 2025). "Later, a class of PCNA inhibitors termed PCNA-Is emerged as potential anti-tumor agents." (PMID 41170373, 2025). "In addition, the number of PCNA-/METTL3-/TRIB3-positive cells was higher in tumor samples from the Tan-IIA treatment group." (PMID 39910904, 2025). "Similarly, western blot analysis of tumor tissues confirmed that DT‐13 suppressed PCNA and Bcl‐2 expression." (PMID 41476787, 2025). "Based on these data, we inferred that Con-A + SB-treated cells had significantly lower expression levels of proteins linked to tumor formation, such as JAK1, STAT3, PCNA, cyclin D1, along with evidence of G2/M phase arrest, as indicated by the downregulation of Cyclin B and Cdk1." (PMID 40350446, 2025). "The small molecule inhibitor AOH1996 targets a cancer-associated isoform of PCNA, suppressing tumor growth without noticeable side effects." (PMID 40430573, 2025). "Furthermore, the expression of Ki-67 and PCNA was significantly increased in HCC cells overexpressing SNX17 tumor tissues." (PMID 40303303, 2025). "Rg3 NPs manifested the downregulation of PCNA and upregulation of Caspase-3 towards tumor death." (PMID 40141242, 2025). "In addition to apoptosis-related markers, CA administration was associated with reduced expression of cell proliferation proteins, including PCNA and Cyclin D1, indicating potential suppression of tumor cell replication." (PMID 40453666, 2025). "PD‐1 blockade with anti‐mPD‐1 monoclonal antibodies (mAb) significantly delayed primary tumor progression, reduced proliferation marker levels (PCNA, Ki‐67), enhanced apoptosis (as indicated by increased cleaved PARP levels), and selectively impaired PI3K/AKT signaling." (PMID 41208884, 2025). "Targeting PCNA and meprin β could offer therapeutic strategies to limit tumor growth and inflammation-driven progression in kidney injury and cancer." (PMID 39975921, 2025). "In neoplastic cells, owing to certain genetic or epigenetic alterations, the expression level of PCNA may be upregulated, leading to accelerated DNA replication, uncontrolled cell proliferation, and ultimately facilitated tumor growth." (PMID 41132724, 2025). "Cells in control tumor samples had PCNA+ staining of 67 ± 10.1% at variable intensity." (PMID 40868059, 2025).
tumor (continued). "Additionally, IHC showed that CDCA7 level was positively correlated with the expression of the proliferation indicators Ki-67 and PCNA in subcutaneous tumor tissues derived from mice." (PMID 39905019, 2025). "PCNA, a marker of tumor cell proliferation, was evaluated via IF staining." (PMID 40956367, 2025). "The impact of PCNA gene expression in patient survival outcomesin various tumor types was examined." (PMID 40657100, 2025). "Moreover, NaB and aspirin treatment lowered the extent of inflammation, reduced tumor heterogeneity, and decreased the number of tumor cells expressing Ki67 and PCNA (both markers of cell proliferation)." (PMID 41251471, 2025). "Our findings indicate that PCNA expression correlates with cell proliferation, and skimmianine may have a suppressive effect on tumor growth." (PMID 40430573, 2025). "Also, cell proliferation was inhibited, as evident by the low expression, at almost 50% compared to the control group of PCNA (proliferating cell nuclear antigen) and Myc-oncogene (a key regulator of tumor microenvironment) in the treatment group." (PMID 40699824, 2025). "Sgg can enlist CD11b+TLR4+ cells, promoting the expression of IL-8, COX-2, and IL-1, and escalating the levels of tumor progression-related transcription factors like β-catenin, c-Myc, and PCNA, thereby driving inflammation and facilitating tumor proliferation." (PMID 40370465, 2025). "Western blot analysis of tumor lysates showed that anti-mPD-1 treatment led to a reduction in F4/80, PD‐L1, Ki‐67, and PCNA levels, suggestive of reduced macrophage infiltration and tumor cell proliferation, although only the decrease in PCNA reached statistical significance." (PMID 41208884, 2025). "In addition, the tumor section in EST mice indicates strong reaction for PCNA expression, although moderate reaction was observed in EST + Free DOX group." (PMID 41039030, 2025). "PCNA plays a crucial role in DNA replication, repair, and cell cycle regulation, which has led to its recognition as an important biomarker in oncology, particularly regarding tumor development and cancer progression." (PMID 41170373, 2025). "PCNA, a marker of cell proliferation, is exclusively expressed in proliferating cancer cells and may contribute to their growth and tumor formation." (PMID 40005158, 2025). "PCNA is related to tumor cell proliferation, and Caspase-3 is related to apoptosis." (PMID 40141242, 2025). "To evaluate the effect of METTL3 O-GlcNAcylation on HCC tumorigenesis in vivo, we performed xenograft experiments in nude mice, which showed that METTL3 depletion significantly hindered HCC growth, as indicated by decreased tumor volume, weight, and proliferating cell nuclear antigen IHC." (PMID 40651967, 2025). "In contrast, treatment with 5-ASA and Doenjang samples (DJA–DJD) significantly reduced PCNA expression, suggesting that Doenjang suppresses abnormal cell proliferation and may help inhibit tumor progression in CAC." (PMID 41154100, 2025). "Unlike previous studies, tumor-specificgenetic alterations, such as amplification and hypomethylation, andthe paradoxical immune microenvironment linked to PCNA were explored,suggesting potential immune evasion mechanisms." (PMID 40657100, 2025). "Furthermore, immunohistochemical assessment of tumor cell proliferation demonstrated a substantial proportion of PCNA-positive cells in the OXP and OXP/BVZ groups, comprising up to 50% of the total cell population." (PMID 40940848, 2025). "Notably, Lipro1 exhibited no significant biotoxicity, but its administration markedly inhibited the anti‐tumor effects of sgFABP5, as confirmed by increased PCNA expression in Lipro1‐treated cells relative to the RFA+FSRP group." (PMID 40956367, 2025). "Conversely, PCNA was notably downregulated in these two groups compared with the tumor group." (PMID 40045239, 2025).
tumor (continued). "Additionally, the expression of EMT markers and proliferation-associated proteins such as PCNA and TGF-β were reduced, indicating a reversion of aggressive tumor phenotypes." (PMID 41019043, 2025). "Additionally, erinacine S treatment correlated with decreased expressions of p-AKT, p-ERK, HIF1α, PCNA, and NFκB p50 in the tumor region of the HCT-116/FUR xenograft in nude mice." (PMID 41209562, 2025). "In advanced stages, TGF-β drives tumor cell proliferation, often reflected by high PCNA expression." (PMID 40507884, 2025). "Moreover, HE, Ki67, and PCNA staining of the primary tumor indicated that the combination of CJP–TiN+L with the α‐PD1 antibody significantly inhibited tumor cell proliferation, emphasizing its superiority in terms of synergistic antitumor effects." (PMID 40387011, 2025). "PCNA was commonly used as markers of tumor cell proliferation." (PMID 40231267, 2025). "Furthermore, we assessed the impact of PCNA knockdown on tumor growth in a HepG2 xenograft model using nude mice." (PMID 40313621, 2025). "This suggests that while IFN-γ-driven responses play a crucial role in eliminating tumor cells, the simultaneous overexpression of PCNA and TNF-α may act as an adaptive mechanism for immune evasion and resistance to immune-mediated cytotoxicity." (PMID 40430573, 2025). "Moreover, the orthotopic model indicated that knockdown of USP27X‐AS1 led to a lower tumour burden, lower PCNA and impaired intrahepatic metastasis ability compared to control." (PMID 38279869, 2024). "Also, multi-color immunofluorescence assay revealed that the combination therapy inhibited the expression of PCNA, a biomarker of tumor cell proliferation, and promoted Cleaved Caspase 3 (Cl." (PMID 38164171, 2024). "Levels of Ki-67 and PCNA were increased in tumor tissue when MEX3C was silenced." (PMID 38424632, 2024). "Notably, PCNA expression positively correlates with PA invasiveness, emphasizing its significance in tumor aggressiveness." (PMID 39688352, 2024). "Our research findings indicate a significant correlation between GR immunohistochemical expression and various factors related to tumour progression, such as tumour histological grade (G), depth of invasion (T), staging, lymph node involvement (N) and PCNA immunohistochemical expression." (PMID 38256170, 2024). "Furthermore, IHC staining showed that CFZ treatment reduced the expression of proliferation markers (Ki67 and PCNA) in HCC xenograft tumor sections." (PMID 38591121, 2024). "In addition, IHC staining was performed on tissue sections of intracranial transplanted GBMs in nude mice to determine changes in the proliferation ability of tumor cells primarily by targeting two cell cycle-related molecules, Ki67 and PCNA." (PMID 39247813, 2024). "ARNTL upregulation reduced tumor cell growth in murine models and decreased PCNA and Ki67 levels." (PMID 39341782, 2024). "In addition, the protein expression levels of KI67 and PCNA were lower in tumor samples treated with cynaroside than those treated with DMSO." (PMID 38611789, 2024). "Additionally, the tumor weight and percentage of Ki-67- and PCNA-positive cells in subcutaneous tumors with KIAA1429 inhibition were significantly lower." (PMID 38902717, 2024). "In addition, PCNA, a marker of cell proliferation, was also highly expressed in tumor tissues compared to adjacent normal tissues." (PMID 39738726, 2024). "Our research findings indicate a significant correlation between Grx1 immunohistochemical expression and various factors related to tumor progression, such as tumor histological grade, depth of invasion, angioinvasion, staging, lymph node involvement, and PCNA immunohistochemical expression." (PMID 38256082, 2024). "Moreover, the immunofluorescence assay showed that PCNA and Ki67 were significantly downregulated in tumor tissues of the ARNTL-ov group compared with those in the vec group." (PMID 39341782, 2024). "Increased expression of VEGF, PCNA, and vimentin was observed in the tumor tissue." (PMID 39029008, 2024).
tumor (continued). "The PCNA+ TAMs are specifically associated with hormone receptor negative high-grade tumours and a decrease in recurrence free survival." (PMID 39205238, 2024). "Tumor tissue was sectioned and subjected to HE staining and PCNA staining." (PMID 39742309, 2024). "In addition, immunohistochemistry staining for PCNA verified that the drug decreased the expression of the tumor proliferation marker PCNA." (PMID 38563878, 2024). "Additionally, a significant difference was also found between the DSEMs and SCTs (**), further highlighting the lower expression of PCNA in SCTs compared with other tumor types." (PMID 39272404, 2024). "Ki-67 and PCNA are the indicators of tumor cell proliferation." (PMID 38730434, 2024). "Based on the results of the immunoblotting experiments, treatment with Orp not only reduced the expression of full-length PARP (implying that Orp promoted the cleavage of the apoptotic protein PARP) in tumor tissues but also inhibited the protein expression of PCNA." (PMID 38356709, 2024). "Additionally, the expression of NR4A3 was negatively correlated with Ki67 and PCNA in NR4A3 knockout or knockdown tumor tissues collected from nude mice with tumor xenografts." (PMID 39664575, 2024). "By inhibiting the NKp44 receptor, PCNA facilitates tumour immune evasion promoting tumour survival." (PMID 39205238, 2024). "As the shelterin disruption by TPP1 removal from clara cells demonstrated metabolic telomere dysfunction, polymorphisms in DNA damage repair genes, and telomere dysfunction, tumor proliferative markers such as proliferating cell nuclear antigen (PCNA) and Ki67 were assessed." (PMID 38344410, 2024). "Understanding the difference in isoforms and location of PCNA in different cell types may explain the role of PCNA within the tumour microenvironment." (PMID 39205238, 2024). "In addition, mice receiving injections of T cells that were pre‐cultured with G‐CSF/GM‐CSF or Mcl‐1 antibody‐treated TCNs exhibited increased CD8+ T cell infiltration and decreased Ki67‐ or PCNA‐positive cells, indicating reduced proliferation of tumor cells." (PMID 39447112, 2024). "ANGPTL4 overexpression could promote OC cell growth (tumor weight and volume) with higher expression of vimentin, proliferating cell nuclear antigen (PCNA), MMP9, ESM1 and CD34, which could be rescued by AG490." (PMID 38212795, 2024). "Moreover, solanine significantly downregulates key inflammatory and proliferative markers, such as iNOS, IL-6, Cyclin D1, and PCNA, reducing tumor growth and inflammation." (PMID 39124760, 2024). "The levels of PCNA and Ki67 were notably reduced in the tumours dissected from the shIGFBP7 group." (PMID 39351597, 2024). "However, tumor tissues in Dnajb4–/– mice showed enhanced cell proliferative activity, as indicated by increased PCNA staining." (PMID 39738726, 2024). "Moreover, IHC analysis revealed a notable decrease in the expression of proliferative proteins Ki67 and PCNA in ACADL overexpressing tumor tissues, which was partially reversed in the XMU-MP-1 treatment group." (PMID 38402174, 2024). "Additionally, P21 expression acts as a suppressor of tumor growth and exhibits specific functions during the S-phase, regulating genomic stability through its interaction with PCNA." (PMID 38687509, 2024). "Moreover, the Ki67 and PCNA percentage area of tumor cells was relatively decreased in NR4A3-overexpressing group when compared with the vector control group." (PMID 39664575, 2024). "The enhancement of apoptosis (increased cleaved caspase 3 and PARP1 levels) and reduction in tumor cell proliferation (decreased Ki67 and proliferating cell nuclear antigen (PCNA) levels) by VSV-S treatment were demonstrated by Western blot analysis of tumor tissues." (PMID 39409870, 2024). "In addition, IHC staining indicated the Ki67 and PCNA expression levels were significantly lower in the combination treatment group, which confirmed the powerful anti-tumor effect of imperatorin plus gemcitabine regimen in PDAC." (PMID 38914663, 2024).
tumor (continued). "Moreover, the immunohistochemical analysis of tumor cell proliferation revealed a comparable fraction of PCNA-positive cells in the tumor tissue of all three groups." (PMID 39075095, 2024). "Studies have shown that MSC-Exo activated the extracellular signal-regulated protein kinase 1/2 (ERK1/2) signalling pathway or upregulated the expression of proliferating cell nuclear antigen (PCNA), accelerated tumour angiogenesis, and further promoted tumour development." (PMID 38302430, 2024). "The tumor tissues were then analyzed by Western blotting to detect the different expression levels of proliferation (Ki67 and PCNA), apoptosis (c-Casp3, c-PARP), metastasis (vimentin), related substrate (p-PDH, HDAC1), and cell cycle-related proteins (CDC25A, CDK4, CDK6, and Rb) in each group." (PMID 38948069, 2024). "PCNA staining was performed to determine the proliferation rate of the tumor tissues." (PMID 37998737, 2023). "IHC analysis of tumor tissue samples showed that FBXO28 upregulation enhanced the staining of the proliferation-associated genes Ki67 and proliferating cell nuclear antigen (PCNA), with a significantly higher proportion of positive cells in the FBXO28 upregulation group than in the control group." (PMID 37348029, 2023). "In this case, tumour grade, depth of invasion, PCNA expression, and staging were considered." (PMID 37242524, 2023). "Proliferating cell nuclear antigen (PCNA) was used to indicate tumor proliferation." (PMID 36969053, 2023). "Furthermore, the T4O treatment resulted in lower levels of KI67 and PCNA protein expression in the tumor tissues compared with the DMSO treatment." (PMID 37375197, 2023). "Proliferating cell nuclear antigen (PCNA) is closely related to DNA synthesis and plays an indispensable role in cell proliferation, which can be used as an indicator to evaluate the status of tumor tissue proliferation." (PMID 37234705, 2023). "PCNA is highly expressed in proliferating cells, especially during the G1 and S phases of the cell cycle, and an increase in PCNA-positive cells in tumor tissues may indicate a poor prognosis." (PMID 37175975, 2023). "In addition, tumor in soft group showed lower proliferating cell nuclear antigen (PCNA) expression than stiff group, indicating that reduced matrix stiffness inhibits tumor proliferation in vivo." (PMID 36684109, 2023). "Notably, in Basal-SCCIS-tumor cells, DNA damage response-related replication genes (PCNA, MCM7) were significantly up-regulated." (PMID 38099574, 2023). "Moreover, the sections of xenografts were subjected to IHC analysis for evaluating expression of Ki-67 and PCNA as a representation of tumor growth, indicating lower proliferation activity of xenograft removed from mice implanted with MCM8 silenced RKO cells." (PMID 37710286, 2023). "The tumor tissue proliferation indicators PCNA and Ki-67 reflect the proliferation status of cells." (PMID 37498338, 2023). "Ki-67 and PCNA are commonly used as measures of tumor cell proliferation." (PMID 37511298, 2023). "The suppression of PCNA was found to hinder the growth of tumor cells." (PMID 38067602, 2023). "High Notch4 expression was markedly correlated with the histological grade of the tumour (p < 0.001, Chi2 test), depth of invasion (p < 0.001, Chi2Yatesa test), angioinvasion ((p < 0.001, Chi2Yatesa test) and PCNA immunohistochemical expression (p < 0.001, Chi2Yatesa test)." (PMID 37108670, 2023). "Analysis of the correlation scatter plot of the IHC score showed DPY30 protein level was positively correlated with PCNA (R = 0.6954, P = 0.0040), Ki67 (R = 0.6691, P < 0.0064) and cyclin A (R = 0.7474, P < 0.0014) in subcutaneous xenograft tumor tissues, respectively." (PMID 37324189, 2023). "Moreover, METTL16 knockdown led to increased expression of Ki-67 and PCNA, two proteins correlated with cancer cell proliferation, according to IHC staining, which was in line with the results of mouse tumor growth." (PMID 37182151, 2023).